CALCRL (calcitonin receptor like receptor)
Diseases named in the same sentence as CALCRL in open-access papers (continued):
Sharing a sentence is not in itself a finding about the gene and the disease.
angle-closure glaucoma (1 paper, 2009). The sudden increase of intraocular pressure, resulting in pain and an abrupt decrease in visual acuity. "Taken together we expected that the degree of expression of CALCRL and the receptor activity of its product would affect the occurrence or development of angle closure glaucoma." (PMID 19898635, 2009).
bronchopulmonary dysplasia (1 paper, 2023). Bronchopulmonary dysplasia is a chronic respiratory disease that results from complications related to lung injury during the treatment of infant acute respiratory distress syndrome in low-birth-weight premature infants or from abnormal lung development in older infants. "It has also been confirmed that the signaling from CALCRL/AM ligation and endothelial nitric oxide synthase activity is important for the resolution of experimental bronchopulmonary dysplasia associated with pulmonary hypertension, clinically seen amongst infants." (PMID 37113606, 2023).
coronary artery disease (1 paper, 2025). "Notably, these ox-LDL-induced dynamic binding sites are enriched for the genetic risk of coronary artery disease, enabling the discovery of the gene-environment interaction of rs62172376 and ox-LDL at the CALCRL/TFPI locus." (PMID 40593292, 2025).
endothelial dysfunction (1 paper, 2025). In vascular diseases, endothelial dysfunction is a systemic pathological state of the endothelium (the inner lining of blood vessels) and can be broadly defined as an imbalance between vasodilating and vasoconstricting substances produced by (or acting on) the endothelium. "As a potent vasodilatory peptide, ADM signals through the calcitonin receptor-like receptor (CLR) coupled with receptor activity-modifying proteins (RAMPs), providing protection against endothelial dysfunction in multiple disease models." (PMID 41515590, 2025).
ischemic stroke (1 paper, 2025). A stroke disorder caused by obstruction of blood flow to the brain, due to thrombotic (local blood clot formation) or embolic (due to a blood clot or other material traveling from another site) event. "In the MR analysis with ischemic stroke as the outcome, we identified 20 positive results, including myeloperoxidase (MPO), CALCRL, and TPGS2." (PMID 40624693, 2025). "In ischemic stroke, we found that MPO, CALCRL, PPP5C, KTN1-AS1, CCR1, CTB-50L17.9, CCR9, ZNF362, ZIK1, ELP5, CKAP2, NUP88, and SEC16A show risk effects (OR > 1)." (PMID 40624693, 2025).
liver cancer (1 paper, 2023). An epithelial or non-epithelial malignant neoplasm that arises from the liver. "Meanwhile, DEPDC1, DEPDC1B, CALCRL, PRR11, and TRIP13 were significantly upregulated in liver cancer tissue, yet NGFR was downregulated." (PMID 36785674, 2023).
lymphoma (1 paper, 2023). A malignant (clonal) proliferation of B- lymphocytes or T- lymphocytes which involves the lymph nodes, bone marrow and/or extranodal sites. "We found that thyroid carcinomas, parathyroid adenomas, pancreatic neuroendocrine tumours, renal clear cell carcinomas, and lymphomas exhibited strong CALCRL expression in a high percentage of specimens." (PMID 36835377, 2023).
metastatic cancer (1 paper, 2018). A carcinoma which has spread from the original site of growth to another anatomic site. "Our data show that NPs strongly modify the chemokinetic capabilities of a cellular line commonly used as a model of metastatic cancer to bone (MDA-MB-231LUC+) and increased the expression of their receptors (NK1R, NK2R, RAMP1, and CALCRL) on these cells." (PMID 30598641, 2018).
neuroendocrine tumour (1 paper, 2023). "We confirmed antibody specificity via Western blot analyses and immunocytochemistry using the CALCRL-expressing neuroendocrine tumour cell line BON-1 and a CALCRL-specific small interfering RNA (siRNA)." (PMID 36835377, 2023).
tumor (29 papers, 2005 to 2025). "Knockdown of CALCRL was also found to limit tumor growth and chemotherapy resistance in animal models." (PMID 41163355, 2025). "To investigate the effect of CGRP in immune modulation, we performed cell-cell communication analysis and multi-immunohistochemical staining, finding that tumor-produced CGRP affected DCs through the CGRP receptor CALCRL." (PMID 39030177, 2024). "Together, these results indicate that tumor cell derived adrenomedullin promotes tumor growth through the endothelial CALCRL/Gs signaling pathway." (PMID 36374225, 2023). "Adrenomedullin is expressed both in endothelial cells and tumor cells and can induce the proliferation of both endothelial cells and tumor cells in a CALCRL- and Gαs-dependent manner." (PMID 36374225, 2023). "Accordingly, co-expression of CALCRL with all three RAMP isoforms was detected in all examined tumour entities." (PMID 36835377, 2023). "Subsequent immunofluorescence double-labelling experiments performed on various CALCRL-positive tumour specimens revealed that RAMP2 expression was predominant, with slightly lower expression of RAMP1." (PMID 36835377, 2023). "As indicated by the minimum and maximum IRS values assigned to individual tumours within each of the different tumour entities and by the respective standard deviations, CALCRL expression exhibited substantial interindividual variability." (PMID 36835377, 2023). "In contrast to our data, it has been reported that an endothelium-specific knock-out of RAMP2, which together with CALCRL forms the adrenomedullin receptor, affects both retinal angiogenesis and tumor angiogenesis." (PMID 36374225, 2023). "In solid tumors, antibody-mediated inhibition of CALCRL signaling has been shown to reduce tumor growth and it is currently being examined as a new and promising candidate therapeutic target for AML." (PMID 35342399, 2022). "Adrenomedullin (AM), a multifunctional peptide plays an important role in angiogenesis and tumor growth through its receptors calcitonin receptor-like receptor/receptor activity modifying protein-2 and -3 (CLR/RAMP2 and CLR/RAMP3)." (PMID 28178651, 2017). "Additionally, single cases with strong CALCRL expression were observed in many of the other tumour entities." (PMID 36835377, 2023). "In these tumours with strong expression of CALCRL, the receptor may represent a useful target structure for future therapies." (PMID 36835377, 2023). "In addition to the confirmation of previous findings, this antibody enabled us to provide the first descriptions of CALCRL expression in many tumour entities." (PMID 36835377, 2023). "Surprisingly, tumor cell proliferation was also reduced after endothelial deletion of CALCRL or Gs." (PMID 36374225, 2023). "Because such expression may have therapeutic relevance, further investigations with larger numbers of cases should be conducted in these and other tumour entities with strong expression of CALCRL." (PMID 36835377, 2023). "In contrast, but consistent with public databases, all primary tumours had detectable message for CALCRL and all RAMPs with one cell line losing detectable CALCRL expression along with 3 xenografts, one xenograft losing RAMP2 and 7 cell lines and 5 xenografts having no detectable RAMP3." (PMID 30777055, 2019). "Down-regulation of CALCRL expression in the tumor and in response to estrogen may implicate two important aspects of the tumor growth, that is, cell proliferation and angiogenesis." (PMID 17407572, 2007). "Consistent with a role of tumor cell–derived adrenomedullin in endothelial and tumor cell proliferation under co-culture conditions, MLECs showed increased proliferation when exposed to conditioned medium of B16-F10 cells, an effect lost after knock-down of endothelial Gαs and CALCRL." (PMID 36374225, 2023). "In these tumours, CALCRL may represent a useful target structure for future therapies." (PMID 36835377, 2023).
tumor (continued). "Therefore, CALCRL mediates the occurrence and development of tumor cells such as CGRP and ADM." (PMID 34712139, 2021). "The results showed that IL2RA, DNMT3B, ADRM1, and NRIP1 were highly expressed in tumor tissue compared to normal tissue, while ALDH2, NYNRIN, LSP1, and CALCRL were the opposite." (PMID 38322112, 2024). "In contrast to adrenomedullin (and CGRP), minimal information is available concerning the expression patterns of CALCRL and the various RAMP isoforms in human tumours." (PMID 36835377, 2023). "Contemporarily, the protein levels of CALCRL and GNAI1 were also higher in innate resistant cells and mice tumor." (PMID 36081671, 2022). "Regarding the activation of tumor angiogenesis, the most prominent targets of HIF-1α are vascular endothelial growth factor (VEGF), calcitonin receptor-like receptor (CRLR), stem cell factor (SCF) and angiopoietin 2 (ANGPT2)." (PMID 27929432, 2016). "Consistently, loss of endothelial CCL2 or tumor cell CCR2 normalized the reduced tumor growth seen in mice lacking endothelial CALCRL or Gs." (PMID 36374225, 2023).
cancer (17 papers, 2012 to 2025). A tumor composed of atypical neoplastic, often pleomorphic cells that invade other tissues. "By integrating transcriptomic and proteomic data in multitrait colocalization, 13 pleiotropic loci influenced CAD and cancer risk via differential gene or protein expression of neighboring genes, including CALCRL, ANGPTL4, and LAMC1, targets of approved or investigational medications." (PMID 40874306, 2025). "Surprisingly, we found one unique gene common to these three independent transcriptomic datasets: CALCRL, encoding a G protein-coupled seven-transmembrane domain receptor poorly documented in cancer that has been recently described as associated with a poor prognosis in AML28." (PMID 33462236, 2021). "Although the results of our study are inconsistent with those of previous studies of other cancers, they further support a close relationship between CALCRL and cancer." (PMID 35087751, 2021). "Rather studies have focused on the angiogenic role of the CGRP/RAMP1/CALCRL complex instead its direct effects on cancer cells." (PMID 30598641, 2018). "The presence of these receptors (NK1R, NK2R, RAMP1, and CALCRL) and the pro-tumorigenic effects of their activating NPs have been demonstrated in a piecemeal fashion across several types of cancer cell lines over the past two decades." (PMID 30598641, 2018). "As expected, we demonstrate the presence of these receptors (NK1R, NK2R, RAMP1, and CALCRL) in MDA-MD-231LUC+ cancer cells." (PMID 30598641, 2018). "There is a large literature about the presence of these receptors (NK1R, NK2R, RAMP1, and CALCRL) in different types of cancer cells." (PMID 30598641, 2018). "Moreover, the relative abundance of human RAMP1- and CALCRL-expressing cells is maintained in the human cancer cells in the orthotopic xenografts." (PMID 37443709, 2023). "Expression of RAMP1 and CALCRL in oral precancer and cancer cell lines was confirmed with qRT-PCR." (PMID 37443709, 2023). "RAMP1 functions in cancer cells may extend beyond signaling with CALCRL." (PMID 37443709, 2023). "Our results also suggest that CALCRL may play different roles in different cancers." (PMID 35087751, 2021). "These included multitrait colocalization at 6 loci with a consistent direction of effect between CAD and cancer (ABO, PGAP3, ANGPTL4, SREBF1, HAUS6, and SYNJ2BP) and 7 with an opposing direction (CDKN1A, RGS19, CALCRL, SF3A3, LAMC1, MYO9B, and MIA3)." (PMID 40874306, 2025).
hematological diseases (1 paper, 2022). "Next, we detected the CALCRL expression level in 67 AML/ETO+ AML patients and 16 patients with nonmalignant hematological diseases using qRT-PCR and identified its prognostic relevance." (PMID 35342399, 2022).
CALCRL also shares sentences with these, for which no sentence is quoted: depression (3 papers); Obesity (3); adenomyosis (2); Anxiety (2); cardiovascular disease (2); endometriosis (2); essential hypertension (2); Ewing sarcoma (2); Lymphangiectasia (2); preeclampsia (2); Alzheimer disease (1); anemia (1); arrhythmogenic right ventricular cardiomyopathy (1); Arthritis (1); Astrocytoma (1); bladder cancer (1); bone metastasis (1); brain tumour (1); calcification (1); Cognitive impairment (1); colon carcinoma (1); endometritis (1); extraskeletal osteosarcoma (1); gastric cancer (1); hydrops fetalis (1); Hyperglycemia (1); hypertriglyceridemia (1); infection (1); insomnia (1); Kaposi's sarcoma (1).
A further 33 diseases each share a sentence with CALCRL in 1 paper.